NFKBIB (NFKB inhibitor beta)
Description:
Inhibits NF-kappa-B by complexing with and trapping it in the cytoplasm. However, the unphosphorylated form resynthesized after cell stimulation is able to bind NF-kappa-B allowing its transport to the nucleus and protecting it to further NFKBIA-dependent inactivation. Association with inhibitor kappa B-interacting NKIRAS1 and NKIRAS2 prevent its phosphorylation rendering it more resistant to degradation, explaining its slower degradation.
Synonyms: IKBB; TRIP9
Tractability: Small molecule: a structure with a bound ligand is known. PROTAC: ubiquitination databases record sites on it; its protein half-life has been measured.
Safety:
Unwanted effects reported when the protein is acted on. In parentheses: how it was acted on, where the effect was seen, and who reports it.
hepatotoxicity (source: ClinPGx)
Gene: Protein-coding gene on chromosome 19 (38,899,700 to 38,908,893, forward strand). Ensembl gene ENSG00000104825.
Subcellular location: Cytoplasm; Nucleus
Subcellular location (Human Protein Atlas): Nucleoplasm; Cytosol
Pathways (Reactome):
Immune System: Activation of NF-kappaB in B cells; RIP-mediated NFkB activation via ZBP1; TAK1-dependent IKK and NF-kappa-B activation; TRAF6 mediated NF-kB activation
Disease: Dengue virus modulates apoptosis
Gene Ontology:
Molecular function: protein binding; transcription coactivator activity
Biological process: cellular response to lipopolysaccharide; DNA-templated transcription; signal transduction; positive regulation of DNA-templated transcription
Cellular component: cytosol; cytoplasm; nucleus
Genetic constraint (gnomAD): Loss-of-function variants: 16 observed, 29.24 expected, observed/expected ratio (o/e) 0.55, 90% interval 0.37 to 0.83. The upper end of that interval is the gene's LOEUF score, 0.83, which puts it in group 3 of 6, group 1 being the genes least tolerant of losing a copy. Missense variants: 437 observed, 496.71 expected, observed/expected ratio (o/e) 0.88, 90% interval 0.81 to 0.95. Synonymous variants: 222 observed, 211.28 expected, observed/expected ratio (o/e) 1.05, 90% interval 0.94 to 1.17.
Homologues: Orthologues: macaque NFKBIB (97% identical), dog NFKBIB (88% identical), pig NFKBIB (88% identical), guinea pig NFKBIB (87% identical), rabbit NFKBIB (86% identical), mouse Nfkbib (85% identical), rat Nfkbib (82% identical), chimpanzee NFKBIB (75% identical), Drosophila melanogaster mask (39% identical), Drosophila melanogaster cact (24% identical), Caenorhabditis elegans mask-1 (15% identical), Caenorhabditis elegans ipla-7 (14% identical), and 1 more. Paralogues in human: NFKBIA (29% identical), TONSL (26% identical), PLA2G6 (19% identical), ANKRD22 (9% identical).
Diseases named in the same sentence as NFKBIB in open-access papers:
NFKBIB is named in the same sentence as 35 diseases in open-access papers, as found by Europe PMC text mining. Sharing a sentence is not in itself a finding about the gene and the disease. The quoted sentences say what the papers report.
breast carcinoma (3 papers, 2016 to 2025). "In gastric cancer cell lines, miR-20a was shown to target NFKBIB, and miR-182-5p was shown to target NFKBIB in breast cancer cells." (PMID 28448456, 2017). "Although one of the real microgravity studies with human breast cancer cell lines indicated an upregulation of NFKB1, NFKB3, NFKBIA, and NFKBIB but a reduced protein content." (PMID 40577073, 2025).
Epithelial Ovarian Cancer (2 papers, 2009 to 2014). "We used a case-control study to evaluate the association between single nucleotide polymorphisms (SNPs) in NFKBIA and NFKBIB (the genes encoding IκBα and IκBβ, respectively) and risk of epithelial ovarian cancer." (PMID 19500386, 2009). "Because of NF-κB's central role in numerous cancer-related processes and involvement in risk of others cancers, we hypothesized that inherited variation in the genes encoding the key inhibitors IκBα and IκBβ (NFKBIA and NFKBIB, respectively) is associated with ovarian cancer risk." (PMID 19500386, 2009). "Considering the number of single-SNP tests performed and null gene-level results, we conclude that NFKBIA and NFKBIB are not likely to harbor ovarian cancer risk alleles." (PMID 19500386, 2009). "To assess whether overall variation within each gene was associated with ovarian cancer risk, we performed multiple logistic regression for participants with complete genotype data (N = 1,901 for NFKBIA, N = 1,930 for NFKBIB)." (PMID 19500386, 2009). "In summary, single-SNP, multi-SNP, and haplotype analyses do not indicate that NFKBIA or NFKBIB harbor risk alleles for ovarian cancer." (PMID 19500386, 2009). "However, considering the number of single-SNP tests performed and the null gene-level results, they concluded that NFKBIA and NFKBIB were not likely to harbor any alleles associated with the risk of ovarian cancer." (PMID 25215581, 2014). "No individual SNPs in NFKBIB were associated with ovarian cancer risk at p < 0.05." (PMID 19500386, 2009). "This study was designed to detect modest genetic associations with ovarian cancer risk; results suggest that common risk alleles of modest effect size may not reside in NFKBIA or NFKBIB." (PMID 19500386, 2009).
colon cancer (1 paper, 2020). "The expression of NFKBIB was remarkably inversely correlated with that of LINC01578 in colon cancer tissues." (PMID 33040438, 2020). "In contrast to LINC01578, NFKBIB was remarkably downregulated in colon cancer tissues with metastasis with respect to colon cancer tissues without metastasis." (PMID 33040438, 2020). "To investigate whether this positive feedback loop also exists in colon cancer metastasis in vivo, we measured the expression and correlation between LINC01578, NFKBIB, and YY1 in clinical tissues." (PMID 33040438, 2020).
depression (1 paper, 2021). "The PPI results of this study show that abnormalities of EC pathways in depression are highly correlated with the up-regulation of NFKBIB." (PMID 34488523, 2021). "Furthermore, we speculate that NFKBIB and HSPB1 play an important role in the relationship between these differential proteins and depression." (PMID 34488523, 2021).
fatty liver disease (1 paper, 2011). A reversible condition wherein large vacuoles of triglyceride fat accumulate in liver cells via the process of steatosis. "Two loci, NFKBIB and RELA, are involved in NFKB signaling pathway; PNPLA3 is known for its association with fatty liver disease; and SH3B2 has been associated with a multitude of traits and disease including myocardial infarction." (PMID 21533024, 2011).
infection (11 papers, 2014 to 2025). The state of being infected such as from the introduction of a foreign agent such as serum, vaccine, antigenic substance or organism. "NFKBIB upregulation of miR-4776 correlated with a decrease in NFKBIB expression within 1 h of infection and a subsequent increase in NFKBIB expression 4 h post-infection." (PMID 28448456, 2017). "Pathways involved in chemokine receptor signaling were also significantly enriched, highlighting the recruitment of immune cells to the site of infection (NFKBIA, NFKBIB, NFKBIE, NFKBIZ, TNFAIP3, REL, BCL3)." (PMID 40634947, 2025). "On the contrary, inhibitory genes of NF-kappaB activity, e.g. IKBKB, NFKBIB and IKBKG decreased over infection time." (PMID 36544767, 2022). "In contrast, the NFKB complex is inhibited by I-kappa-B proteins (NFKBIB) which is a mechanistic gene expressed during MAP infection early stage at 30 minutes post infection and was not expressed thereafter." (PMID 27653506, 2016).
cancer (9 papers, 2009 to 2024). A tumor composed of atypical neoplastic, often pleomorphic cells that invade other tissues. "More interestingly, seven different genes (ECH1, PEX5, MLF2, NFIX, TSPAN9, SAMD4B, and NFKBIB) were associated with another drug C646, which is a small molecule inhibitor targeting histone acetyltransferase p300, an enzyme that alters the cancer transcriptome in the lung, colon and pancreas." (PMID 29207666, 2017). "NFKBIB overexpression in carcinoma cell lines results in reduced NF-κB binding to DNA and downregulation of target gene transcription, with tumour-suppressive effects." (PMID 37228587, 2023). "The genes (CXCL1, CXCL3, CXCL8, NFKBIB, and SRC) associated with chemokine pathway signaling result in changes in the cellular microenvironment that favor cancer and transformation in L-LVL cells." (PMID 34680563, 2021). "A review of the literature revealed that aberrant expression of CKMT1A, GCNT1, NCALD, NFKBIB, NOMO3/Nodal, SLC16A5, or TRPV2 was correlated with cancer." (PMID 31363162, 2019).
tumor (3 papers, 2008 to 2023). "Ratio differences of important immune-related AS events (clualt3p199530 NRG1, clualt5p154454 SH3BP2, clualt5p114936 ACKR3, clualt5p152292 IL15, cluir97910 NFKBIB, and clualt5p204621 IKBKG) between tumor and normal tissues are presented." (PMID 37139238, 2023).
NFKBIB also shares sentences with these, for which no sentence is quoted: atherosclerosis (2 papers); gastric cancer (2); Hepatitis (2); lung carcinoma (2); ovarian cancer (2); preeclampsia (2); asthma (1); bronchiolitis (1); colorectal cancer (1); dengue hemorrhage (1); Endotoxemia (1); gastrointestinal stromal tumor (1); hepatocellular carcinoma (1); Hodgkins lymphoma (1); influenza (1); Insulin resistance (1); knee osteoarthritis (1); leishmaniasis (1); melanoma (1); multiple myeloma (1); myocardial infarction (1); non-small cell lung carcinoma (1); peritoneal adhesions (1); renal disease (1); schizophrenia (1); Sepsis (1); squamous cell carcinoma (1).